IL33 (interleukin 33)
Diseases named in the same sentence as IL33 in open-access papers (continued):
Sharing a sentence is not in itself a finding about the gene and the disease.
infection (continued). "Drug cure resulted in a sudden decrease of most of the cytokines that became overexpressed after primary infection (IL-6, IL-9, IL-12, IL-33, IFN-γ and TSLP)." (PMID 27658962, 2016). "At 24 hours post-infection (hpi), we found an infectious dose-dependent increase in the expression of IL-33, soluble ST2 (sST2), membrane-bound ST2L, and the Ang2/Ang1 ratio." (PMID 26943125, 2016). "Concomitantly with elevated levels of Th1 indicators (IL-12, IFN-γ and iNOS), primary infections induced increased expression of several Th2 markers (IL-33, TSLP, ArgI and Ym-I) and other cytokines such as IL-9." (PMID 27658962, 2016). "We are showing that IL-33 is expressed on the CNS following infection with a neurotropic virus, balancing the local immune response with consequent protection from exacerbated CNS injury." (PMID 27334012, 2016). "We have shown that the mRNA expression of IL-33 and ST2 receptors is increased in the CNS of Rocio virus-infected WT mice and that ST2−/− mice showed increased susceptibility to infection." (PMID 27334012, 2016). "Infection with P. gingivalis appears to promote the PAR-2/IL-33 axis through a gingipain-dependent mechanism in human gingival epithelial cells." (PMID 27058037, 2016). "IL-33 contributes to the initiation of type-2 immune responses following infection with several pathogens and allergens." (PMID 27445267, 2016). "IL-33 protein expression levels were enhanced both after mixed infection and male-only infection while the liver cells of the latter displayed a poor response to IL-33 and a reduction in Th2 cytokine production." (PMID 27445267, 2016). "We therefore analyzed the effects of infection with viable P. gingivalis upon IL-33 mRNA expression in human gingival epithelial (Ca9-22) cells in vitro." (PMID 27058037, 2016). "In this study, we compared the severity of disease between wild-type (WT) and IL-33-/- mice infected with O. tsutsugamushi and used exogenous IL-33 to further examine the function of IL-33 during the infection." (PMID 26943125, 2016). "Conversely, addition of exogenous IL-33 during a sub-lethal infection exacerbated the activation of renal endothelium and lethality." (PMID 26943125, 2016). "Overall, our results have defined a signaling cascade leading to an increase of IL-33 expression in CF AECs in response to an acute infection." (PMID 26793709, 2015). "Neutralizing IL-33 during primary infection in neonates resulted in significant reductions in Th2 and multifunctional Th (mTh; IFNγ+, IL-4+) cells upon reinfection (α-IL-33+NRR)." (PMID 26473724, 2015). "In this study, we address which cells of the gastric mucosa express IL33, how IL33 expression changes with damage and infection, and characterize the function of IL33 in the stomach." (PMID 28210674, 2015). "In this manuscript we investigated the intracellular signaling pathways responsible for increasing IL-33 expression in CFTRdelF508 AECs following an acute infection with Pseudomonas aeruginosa." (PMID 26793709, 2015). "Within 24 h of infection, expression of Il33, Tslp and Ccl20 transcripts were elevated in infected epidermis relative to naïve skin, indicating that the epidermis is a source of stimuli for APCs and T cells." (PMID 25575749, 2015). "IL33 now is recognized as an alarmin, capable of responding to adverse circumstances such as infection or mucosal damage in the lung and colon, and can promote Th2 immunity." (PMID 28210674, 2015). "In keeping with an alarmin function, IL33 mRNA expression is increased acutely after H pylori infection in mice; however, its expression is decreased 2 months after infection." (PMID 28210674, 2015). "Interleukin-33 is stored in the nucleus and secreted upon necrosis or damage and released in response to cell injury, infection or mechanical damage." (PMID 26425339, 2015).
infection (continued). "In children, the production levels of regulatory IL-27 and also of inflammatory IL-33 rose with the number of infections (G0 < G < G3+) and these responses were inducible by mite-allergen extracts." (PMID 25698903, 2015). "Because of these properties, IL-33 is identified as an “alarmin” and is defined as a member of danger-associated molecular pattern (DAMP) molecule for alerting the immune system after infection or injury." (PMID 25658420, 2015). "Highly elevated IL-33 levels were detected in neonates as early as 0.25 days post-infection (dpi) and peaking at 0.5 dpi." (PMID 26473724, 2015). "Our results have shown that TLR-mediated signaling regulates IL-33 expression in the context of infection." (PMID 26793709, 2015). "As a cytokine, extracellular IL-33 is closely involved in Th2 immune responses in allergic and autoimmune diseases and plays a role in the host defense against infection." (PMID 26610488, 2015). "To determine if IL-33 modulation had an impact on overall viral load, we compared the amount of infectious virus in the lungs of treated and control mice at the peak of infection (i.e. 4 dpi)." (PMID 26473724, 2015). "IL33 mRNA expression still was increased 7 days after H pylori–SS1 infection, however, this increase was less than that observed in the 1-day cohort, and was not significantly different from controls (Figure 2Aii)." (PMID 28210674, 2015). "Here, we show that IL33 is a stomach alarmin, which is induced acutely during chemical damage or infection, but is suppressed by chronic H pylori infection." (PMID 28210674, 2015). "It is important to note that IL-33-treated mice produced minimal amount of IL-10 during PbA-infection." (PMID 25659095, 2015). "RV infection induced a dose-dependent increase of IL-33 mRNA in BSMCs from healthy individuals at 24 h being further enhanced 48 h post infection." (PMID 26318341, 2015). "Two months of H pylori–SS1 infection resulted in a significant reduction in IL33 mRNA expression (Figure 2Aiii)." (PMID 28210674, 2015). "SMCs are in direct contact with the stomach lumen and H pylori preferentially localizes to the gastric pits, suggesting that IL33 is placed ideally to mount an effective immune response after infection or injury." (PMID 28210674, 2015). "The importance of IL-33 for parasite control was also demonstrated for N. brasiliensis, where IL-33 is needed in both primary and secondary infection to promote expulsion." (PMID 25028340, 2014). "To understand the immunological relevance of iNOS induced by IL-33 and infection, we next set out to elucidate the biological role of IL-33." (PMID 24586149, 2014). "Here, IL-33 acts as an endogenous danger signal (alarmin), which alerts innate immune cells to sites of infection or injury." (PMID 25175678, 2014). "Type II alveolar epithelial (ATII) cells express IL-33 in their nucleus and infection with Strongyloides venezuelensis induces IL-33 production by increasing the number of ATII cells possibly by the action of chitin." (PMID 24678315, 2014). "Inflammation is critical in mediating the host response to injury or infection, and IL-33 plays an important role through induction, progression, and maintenance of the inflammatory response." (PMID 25136658, 2014). "During the experimental intestinal nematodes (Trichuris muris) infection in mice, IL-33 was markedly elevated soon after infection." (PMID 24507763, 2014). "Mouse skin treated with IL-33 neutralizing antibody exhibited greater S.aureus survival at the local site of infection and a greater S.aureus bacterial burden in skin lesion." (PMID 24586149, 2014). "Although IL-33 has been shown to play a significant role during infection, little is known about how IL-33 is regulated as a mechanism to increase host defense against skin bacterial infections." (PMID 24586149, 2014).
infection (continued). "This occurs because IL-33 inhibits G protein-coupled receptor kinase-1 (GRK-1) downregulation which is induced by TLR signaling during infection by bacteria or fungi." (PMID 23653627, 2013). "IL-1β acts to decrease production of IL-25 and IL-33 at early time points following infection and parasite rejection was determined to require IL-25." (PMID 23935505, 2013). "The LSEC and VEC expressed inducible expression of IL-33 following L2-MHV3 infection but the hepatocyte-specific IL-33 expression was only evident between 24 to 32h of post infection." (PMID 24058536, 2013). "IL-33 also induces the recruitment of neutrophils to sites of infection through the release of chemokines, such as CXCL1, CXCL2, and CCL3, from macrophages." (PMID 23653627, 2013). "The first stage of L. monocytogenes infection involves crossing the intestinal barrier and IL-33 is released upon epithelial damage, so presumably IL-33 is released during infection." (PMID 23460827, 2013). "Its nuclear expression combined with the absence of a peptide signal for export led to the notion that IL-33 is released primarily upon tissue injury or infection and, through binding to ST2L on immune cells, responsible for initiating tissue inflammation." (PMID 23300625, 2012). "Subsequently it was shown that IL-33 is a potent pro-inflammatory danger signal, or alarmin, released from necrotic cells upon trauma or infection." (PMID 23300625, 2012). "To further assess whether IL-33 supplementation impacted tissue damage or infection progression, despite its limited effect on trTregs, we examined plasma levels of biochemical markers indicative of tissue damage." (PMID 39883714, 2025). "Moreover, under conditions of cellular stress, such as infection and tumors, IL‐33 mainly binds to helper proteins (IL‐1RAcP) and receptors (ST2/IL1RL1) on the cell membrane, thereby activating cytokines or downstream signaling pathways." (PMID 40860436, 2025). "RSV and HMPV induced significantly more IL-33 in the adult cells on day 3 after infection." (PMID 40143308, 2025). "Increased sST2 may worsen myocardial injury and infection by obstructing the cardioprotective and immunomodulatory functions of the IL-33/ST2l pathway, thereby creating a detrimental “inflammation-infection” cycle." (PMID 41341291, 2025). "However, there is limited information on the behavior of this subset and their reliance on the IL-33/ST2 axis for controlling infection-induced tissue damage." (PMID 39883714, 2025). "However, preclinical studies have shown that the role of ST2/IL-33 can be either protective or detrimental, depending on the specific infection." (PMID 41163220, 2025). "Lastly, IL-33 was uniquely reduced in the primary infection mice." (PMID 41190814, 2025). "As discussed in the previous section, reduced systemic IL-33 levels during infection may compromise trTreg commitment in secondary lymphoid organs, leading to an overall decrease in trTreg numbers." (PMID 39883714, 2025). "Considering the inconsistent preclinical picture, it is therefore plausible that blocking the ST2/IL-33 pathway may impede the appropriate inflammatory responses to infections in clinical settings." (PMID 41163220, 2025). "IL-33 is a proinflammatory IL-1 family cytokine expressed at epithelial tissue barriers and a nuclear alarmin that alerts innate immune cells and Th2 lymphocytes to injury or infection." (PMID 40100295, 2025). "However, in endothelial cells, the infection results in increased expression of IL33 and its receptor." (PMID 41204030, 2025). "C. difficile burden at day 15 after infection was unaltered by IL-33." (PMID 40048372, 2025). "Moreover, it is known that IL-33 is produced as a defense mechanism against tissue damage (inflammation, infection, etc.)." (PMID 40142865, 2025). "Because of the cross-sectional nature of our data, it remains unclear whether the observed differences in IL-33 levels precede pathogen acquisition or are in fact a result of infection." (PMID 38714349, 2024).
infection (continued). "This important and novel mechanism for IL‐33 has also been proposed by a recent study, in which IL‐33 was reported to induce naive T cell aging by inducing thymic involution in mice during severe infection." (PMID 39465143, 2024). "During the resolution phase of infection event, IL-33 acts on residential ST2-expressing group 2 innate lymphoid cells (ILC2s) as well as regulatory T (Treg) cells to restore airway tissue homeostasis, mediated at least partly by amphiregulin (AREG)-dependent repair of virus-damaged epithelium." (PMID 38704386, 2024). "It is possible that EPAC/PLC-independent calcium release may be also induced by infection, however, the magnitude is too little to contribute significantly to IL-33 production." (PMID 38750790, 2024). "Increased production of TNF-α and IL-12 during infection in the presence of IL-10 neutralizing antibodies further supports the hypothesis and paves avenue to explore the interdependency of IL-33 and IL-10." (PMID 38750790, 2024). "Since PLC activation is intricately associated with intracellular calcium release, we next checked whether calcium is involved in infection-mediated IL-33 production." (PMID 38750790, 2024). "Despite the activation of PKA during infection, its indifference to IL-33 remains to be a mystery and may be attributed to its irregular activation kinetics." (PMID 38750790, 2024). "Besides playing a crucial role in anamnestic immunity, IL-33 is also involved in larvae killing in the primary infection of nematodes." (PMID 39559705, 2024). "In the context of the findings outlined here, we propose the following model for the HpARI family’s effects: HpARI2 binds strongly to the extracellular matrix, and is retained in the local milieu of the parasite where it blocks IL-33 released in response to infection." (PMID 39514278, 2024). "In vitro and in vivo experiments further identified the transcription factors nuclear factor of activated T cell 1 (NFATc1) and hypoxia-inducible factor 1 alpha (HIF-1α), which are activated by calcium-dependent phosphatase calcineurin and lead to IL-33 production during infection." (PMID 38750790, 2024). "A significant decrease in parasite survival was observed by treatment with DDA, which was only partially reversed by the addition of recombinant IL-33, suggesting that IL-33 signaling might be one of the several pathways regulated by cAMP during infection." (PMID 38750790, 2024). "EPAC has been recognized to regulate other infections such as Plasmodium sp., but none was associated with IL-33." (PMID 38750790, 2024). "Finally, double infection with 2 RV serotypes significantly increased both IL-33 mRNA and protein expression." (PMID 38061015, 2024). "Next, we examined how cell death from live infection could intensify IL-33 and LDH levels in the treatments of KERTr cells with live S. aureus, heat-killed S. aureus (HK), or PGN." (PMID 38319737, 2024). "Normally, IL-33 is stored in the nucleus, but is frequently released from both the nucleus and cell in response to tissue damage, necrosis, oxidative stress, inflammation and infection." (PMID 39713054, 2024). "Thus, this study demonstrates that cAMP/EPAC/calcineurin signaling is crucial for the activation of IL-33 and in effect creates anti-inflammatory responses, essential for infection." (PMID 38750790, 2024). "Thus, the current IL-33 high level of the injected groups on days 7, 14, and 21 suggested that it is a sign of protection against P. equorum crude antigen infection." (PMID 39103392, 2024). "Thus, our data suggested the potential collaboration of IL-25 and IL-33 in regulating adaptive T helper cell responses during C. neoformans infection, especially during the late phase of infection." (PMID 37337050, 2023).
infection (continued). "We first isolated hippocampal brain macrophages (including both microglia and recruited peripheral monocyte-derived macrophages) using F4/80 mediated MACS from WT and Il33–/–mice 7 days after intracranial WNV-E218A infection and processed them for RNA sequencing." (PMID 37983247, 2023). "In this brief report, we demonstrate that deficiency of IL-17A leads to impaired IL-33 expression and secretion early in infection, independent of IL-17A suppression of IFN-γ." (PMID 37783278, 2023). "Due to a loss of microglial markers post-infection and a requirement for ST2 expression on microglia to support host survival we sought to identify the transcriptional programs initiated by IL-33 on brain macrophages in total post-infection." (PMID 37983247, 2023). "Stromal and epithelial cells are important sources of IL-33 during infection with Nb22." (PMID 37783278, 2023). "Because it is a cellular alarmin indicating damage and infection, extensive damage of the airway epithelium may contribute to the excessive release of IL-33 and progression toward severe disease." (PMID 37631998, 2023). "In experimental infections with S. japonicum, exogenous administration of IL-33 leads to larger liver granulomas and a stronger Th2 response, whereas inhibition of the IL-33/ST2 pathway hinders fibrosis, collagen deposition, and differentiation of HSCs into myofibroblasts." (PMID 37373379, 2023). "Infections might increase IL-33 expression and secretion in the epithelium and enhance IL-33 in PBMC and peripheral blood lymphocytes (PBL)." (PMID 37240045, 2023). "Our findings showed that the IL-33 treatment could exacerbate infection in the host, potentially via ILC2 expansion." (PMID 36602520, 2023). "More importantly, IL-33 deficiency, the anti-IL-33 neutralizing antibody treatment, or IL-33 receptor ST2 deficient thymus transplantation rescues T cell immunity to better control infection in mice." (PMID 36371464, 2022). "LAD2 MCs were incubated with IL-33 for 24 h prior to HRV16 infection (MOI 7.5) for a further 24 h." (PMID 36366528, 2022). "Indeed, a recent randomized controlled trial shows that MEDI3506 (anti-IL-33) has led to a marked reduction in severe respiratory failure and better control of infection in patients with COVID-1952." (PMID 36371464, 2022). "Mouse models of RSV infection showed that administration of an anti-IL-33-receptor antibody that blocks the IL-33 cascade can reduce both the Th2 and Th17 environment (especially IL-13 and IL-17A) and the eosinophil recruitment induced by IL-33 after infection." (PMID 35327516, 2022). "Amelioration of altered airway responses after secondary infection could also be achieved with administration of an IL-13Rα2 fusion protein, blockade of IgE, blockade of IL-33 signaling, or inhibition of STAT6 during the primary infection." (PMID 35493465, 2022). "Our data suggest that host cells or ASFV may regulate their cytokine response to infection by altering the expression of IL-33 to avoid a cytokine storm and an inflammation." (PMID 36032295, 2022). "IL-33 belongs to the IL-1 family and acts as an alarmin that reveals cellular damage or infection." (PMID 35327516, 2022). "Moreover, exogenous IL-33 enhanced the secretion of IL-12 in bronchoalveolar lavage fluids post-infection, amplified IL-12 production, and increased the maturation of dendritic cells." (PMID 35327516, 2022). "Notably, although no obvious differences in the number or activation state of ILC2s were detected, we also found that the type 2 cytokine Il13 and the related alarmin Il33 were significantly up‐regulated after infection." (PMID 35018740, 2022). "The upregulation of IL-33 with an amebic infection that is part of the host-protective response may act in part by inducing tissue repair mechanisms that enhance blood coagulation and angiogenesis in colonic tissue." (PMID 34400793, 2022).